LARS2 (leucyl-tRNA synthetase 2, mitochondrial)
Description:
Catalyzes the attachment of leucine to its cognate tRNA.
Synonyms: LeuRS; KIAA0028; MGC26121; mtLeuRS; HLASA; PRLTS4
Tractability: PROTAC: ubiquitination databases record sites on it; its protein half-life has been measured.
Target class: Enzyme; Ligase
Gene: Protein-coding gene on chromosome 3 (45,388,527 to 45,554,726, forward strand). Ensembl gene ENSG00000011376.
Subcellular location: Mitochondrion matrix
Subcellular location (Human Protein Atlas): Mitochondria
Pathways (Reactome):
Metabolism of proteins: Mitochondrial tRNA aminoacylation
Gene Ontology:
Molecular function: leucine-tRNA ligase activity; aminoacyl-tRNA deacylase activity; aminoacyl-tRNA ligase activity; ATP binding; nucleotide binding
Biological process: leucyl-tRNA aminoacylation; mitochondrial translation; tRNA aminoacylation for protein translation; aminoacyl-tRNA metabolism involved in translational fidelity
Cellular component: mitochondrion; mitochondrial matrix
Genetic constraint (gnomAD): Loss-of-function variants: 53 observed, 82.51 expected, observed/expected ratio (o/e) 0.64, 90% interval 0.51 to 0.81. The upper end of that interval is the gene's LOEUF score, 0.81, which puts it in group 3 of 6, group 1 being the genes least tolerant of losing a copy. Missense variants: 794 observed, 931.08 expected, observed/expected ratio (o/e) 0.85, 90% interval 0.8 to 0.9. Synonymous variants: 323 observed, 345.18 expected, observed/expected ratio (o/e) 0.94, 90% interval 0.85 to 1.03.
Gene-disease validity (ClinGen):
ClinGen rates the evidence that LARS2 causes each of these diseases.
Perrault syndrome (autosomal recessive): Definitive. Perrault syndrome (PS) is characterized by the association of ovarian dysgenesis in females with sensorineural hearing impairment.
Homologues: Orthologues: chimpanzee LARS2 (99% identical), macaque LARS2 (92% identical), dog LARS2 (91% identical), pig LARS2 (91% identical), rabbit LARS2 (88% identical), rat Lars2 (87% identical), mouse Lars2 (86% identical), guinea pig LARS2 (83% identical), tropical clawed frog lars2 (69% identical), zebrafish lars2 (60% identical), Drosophila melanogaster LeuRS-m (40% identical), Caenorhabditis elegans lars-2 (32% identical). Paralogues in human: VARS1 (19% identical), VARS2 (19% identical), IARS2 (17% identical), IARS1 (17% identical), LARS1 (15% identical), MARS1 (12% identical), MARS2 (10% identical).
Diseases named in the same sentence as LARS2 in open-access papers:
LARS2 is named in the same sentence as 55 diseases in open-access papers, as found by Europe PMC text mining. Sharing a sentence is not in itself a finding about the gene and the disease. The quoted sentences say what the papers report.
Perrault syndrome (26 papers, 2014 to 2026). "In the catalog (CD−M7), Pou3f4, Homer2, and Col11a2 were associated with NSHL, Snai2 with Waardenburg syndrome, Lars2 with Perrault syndrome, and Col11a2 with otospondylomegaepiphyseal dysplasia." (PMID 39684410, 2024). "Biallelic pathogenic variants in HARS2 and LARS2 result in Perrault syndrome, which associates hearing impairment with ovarian dysfunction and, occasionally, a variety of neurological signs." (PMID 39062730, 2024). "Biallelic pathogenic variants in either HARS2 (mtARS for histidine) or LARS2 (mtARS for leucine) result in Perrault syndrome, which associates HI with ovarian dysfunction in females, and manifests as NSHI in males." (PMID 39062730, 2024). "The selective impact of CLPXP on mtLSU was surprising, because Perrault syndrome is triggered by mutant HARS2/LARS2/ERAL1, all of which are associated with the mtSSU." (PMID 38139332, 2023). "Variants in HARS2 and LARS2 are associated with Perrault syndrome manifesting with a wide range of neurological symptoms, variable progression of hearing loss and POI." (PMID 37148394, 2023). "LARS2 (OMIM: *604544) was identified as a Perrault syndrome-associated gene in 2013 (PRLTS4, OMIM: #615300)." (PMID 36693951, 2023). "Mutations in histidyl-tRNA synthetase 2, mitochondrial (HARS2), and leucyl-tRNA synthetase 2, mitochondrial (LARS2), are frequently associated with Perrault syndrome, which often leads to neuropathic hearing impairment and ovarian dysfunction in women." (PMID 35805194, 2022). "Two variants were identified in LARS2 (NM_015340.3): c.1886C > T, p.Thr629Met was previously reported only once in ClinVar related to Perrault syndrome, and the novel c.1481dup, p.(Leu495Thrfs*31)." (PMID 34997062, 2022). "More recently, bi-allelic LARS2 variants have been reported to lead to Perrault syndrome with neurological symptoms." (PMID 36570450, 2022). "LARS2 variants are associated with disorders called Perrault syndrome (OMIM 615300) in most studies, characterized by premature ovarian failure and sensorineural hearing deafness." (PMID 36570450, 2022). "Sequence variants in LARS2 have been previously associated with Perrault syndrome, characterized by premature ovarian failure, hearing loss and other severe multisystem metabolic disorders (OMIM #604544)." (PMID 34997062, 2022). "LARS2 is associated with Perrault syndrome, which is characterized by SN HL in males and females and ovarian dysfunction in females." (PMID 34440452, 2021). "Biallelic variants in CLPP and LARS2 are known to cause Perrault syndrome, a rare autosomal recessive disorder characterized by sensorineural HL in both sexes and primary ovarian failure in females." (PMID 32842620, 2020). "Mutations of five (mt) aaRS genes cause syndromic forms of deafness, including Perrault syndrome (LARS2, HARS2), Charcot Marie Tooth disease type 2N (AARS) and pontocerebellar hypoplasia type 6 (RARS2)." (PMID 25807530, 2015). "Genetic studies indicate that mutations in mitochondrial HARS2 and LARS2 are both linked to Perrault Syndrome." (PMID 24917879, 2014). "More recently homozygous mutations in LARS2, encoding the mitochondrial leucyl-tRNA synthetase (mt-LeuRS), have been found in patients with Perrault syndrome (OMIM#615300)." (PMID 24639874, 2014). "Given that mutations in the mitochondrial leucine tRNA-ligase LARS2 cause the Perrault syndrome just like CLPP deficiency, this observation may further strengthen the notion that RNA processing is important in this pathogenesis." (PMID 38139332, 2023). "To date, 19 variants have been reported in 18 individuals with LARS2-Perrault syndrome." (PMID 32423379, 2020). "Interestingly, hearing problems are present also in patients with PCH6 (due to RARS2 mutations) or Perrault syndrome (caused by LARS2 or HARS2 mutations)." (PMID 24639874, 2014). "Similarly, the LARS2 mutation associated with Perrault Syndrome, T522N, also targets a highly conserved residue located in the catalytic domain." (PMID 24917879, 2014).
Perrault syndrome (continued). "This may have potentially prompted segregation testing of the LARS2 variants and diagnosed Perrault syndrome years before the onset of premature ovarian insufficiency in the proband and would have been helpful for improving overall management of progressive co-morbidities in both individuals." (PMID 36693951, 2023). "The LARS2 variant p.Thr522Asn has been reported in three individuals from Palestine with severe hearing loss and POI associated with Perrault syndrome." (PMID 38737775, 2023). "Mutations in LARS2, encoding mitochondrial leucyl-tRNA synthetase, lead to POI and hearing loss in Perrault syndrome." (PMID 34803902, 2021). "As variants in other tRNA processing factors such as PRORP, HARS2, and LARS2 are a known cause of PRLTS, a common mechanism of disease pathogenesis begins to emerge for Perrault syndrome." (PMID 34943861, 2021). "Pathogenic/likely pathogenic variants in HARS2, CLPP, LARS2, TWNK, ERAL1, and PROPR may cause Perrault syndrome-related OD." (PMID 38812815, 2024). "Nearly 10 years have passed since the initial gene discovery linking LARS2 to Perrault syndrome." (PMID 36693951, 2023). "We identified the c.457A>C (p.Asn153His) variant (ClinVar VCV000191173.2) of LARS2 in a patient with SA, who was not previously associated with Perrault syndrome, and other three missense variants in two SA patients." (PMID 34803902, 2021). "Recently, mutations in mt-aaRS (ARS2) and cytoplasmic aaRS (ARS) have been associated with human diseases such as Charcot-Marie-Tooth disease, Perrault syndrome (LARS2, HARS2), and pontocerebellar hypoplasia, all of which include sensorineural hearing impairment." (PMID 25807530, 2015). "Identification of a variant in LARS2 that segregates in family HL17 is highly clinically relevant, considering that, without this genetic screening, the diagnosis of Perrault syndrome would not be considered in disease clinical management, prognosis, and counseling." (PMID 32842620, 2020). "In LARS2- and HARS2-associated Perrault syndrome, no data were published about the brain imaging, while in CLPP-associated Perrault syndrome, high signal intensity in the corticospinal tract deep white matter could be found." (PMID 31852434, 2019).
hearing loss (8 papers, 2018 to 2026). "Mutations in Lars2 have also been associated with sensorineural hearing loss, hydrops, lactic acidosis, sideroblastic anemia, and multisystem failure." (PMID 33679877, 2021). "A similar pattern has been reported in several patients from the literature, suggesting it could be a distinctive feature of LARS2-associated hearing loss." (PMID 39062730, 2024). "Dysfunction of some mitochondrial aminoacyl-tRNA synthetases (encoded by the KARS1, HARS2, LARS2 and NARS2 genes) results in a great variety of phenotypes ranging from non-syndromic hearing impairment (NSHI) to very complex syndromes, with a predominance of neurological signs." (PMID 39062730, 2024).
lactic acidosis (6 papers, 2019 to 2022). Metabolic acidosis characterized by the accumulation of lactate in the body. "LARS2 has also been associated with HLASA (hydrops, lactic acidosis, and sideroblastic anemia), which is another rare phenotype unique to LARS2." (PMID 36553587, 2022). "Biallelic pathogenic variants of LARS2 can cause a wide phenotypic spectrum, including deafness, ovarian failure, leukodystrophy, and lactic acidosis due to mitochondrial function impairment." (PMID 36158645, 2022). "Here, we also identified a rare case of a syndrome characterized by hydrops, lactic acidosis, and sideroblastic anemia, which was due to a homozygous variant in the LARS2 gene." (PMID 34201899, 2021). "For example, mutations in LARS2 have been reported to cause hydrops, lactic acidosis, sideroblastic anemia, and multisystem failure in a female newborn." (PMID 31455392, 2019).
sideroblastic anemia (6 papers, 2019 to 2022). "To date, six genes have been discovered that may cause sideroblastic anemia: PUS1, YARS2, LARS2, TNRNT1, NDUFB11 and MT-ATP6." (PMID 34441767, 2021).
leukodystrophy (5 papers, 2021 to 2026). Leukodystrophies are a group of rare, progressive, metabolic, genetic diseases that affect the brain, spinal cord and often the peripheral nerves. "Examination of his symptoms revealed a multisystem mitochondrial disorder due to the c.457A>C variant in LARS2, which manifested phenotypically as leukodystrophy, cognitive impairment, epilepsy, hearing loss, myopathy, and spastic tetraparesis." (PMID 42077717, 2026). "In AxD, AGS, CARASAL, LARS2-related leukodystrophy and X-ALD, we found expression of ZO-1 also outside of the NVU." (PMID 34082828, 2021). "Redistribution of AQP4 in AxD, ALSP, PMD, LARS2-related leukodystrophy, X-ALD and CARASAL strongly points towards an astrocytic dysfunction." (PMID 34082828, 2021). "LysRS are involved in myelin formation and defects in other ARSes (e.g., AARS2, DARS2, EARS2, and LARS2) have been found to be responsible for leukodystrophy." (PMID 33942428, 2021). "Disease mechanisms in LARS2-related leukodystrophy are still elusive." (PMID 34082828, 2021). "LARS2-related leukodystrophy belongs to leukodystrophies with myelin vacuolization." (PMID 34082828, 2021).
colorectal cancer (4 papers, 2024 to 2026). A primary or metastatic malignant neoplasm that affects the colon or rectum. "In a murine colorectal cancer model, a leucine-rich diet increased the generation of leucyl-tRNA synthetase 2 (LARS2)-expressing regulatory B cells, which contribute to immune evasion in colorectal cancer." (PMID 39858185, 2025). "Through single-cell technology, a study systematically analyzed tumor-infiltrating B cells at various stages of colorectal cancer and identified a novel subset of B cells (LARS B) characterized by high expression of leucyl-tRNA synthetase 2 (LARS2)." (PMID 38627278, 2024).
Premature ovarian insufficiency (4 papers, 2022 to 2025). Amenorrhea due to loss of ovarian function before the age of 40. "Several studies have indicated that mutations of LARS2 are associated with premature ovarian insufficiency (POI)." (PMID 35585880, 2022). "Analysis of LARS2 expression in human granulosa cells derived from patients with premature ovarian insufficiency (POI)." (PMID 36857094, 2023).
Cognitive impairment (3 papers, 2025 to 2026). Abnormal cognition is characterized by deficits in thinking, reasoning, or remembering. "Experimental evidence indicates that when Lars2 is knocked out in the hippocampus of mice, it results in an elevation of the ROS level, disrupts mitochondrial function, ultimately leads to cognitive impairment." (PMID 40153587, 2025). "These neuromorphological alterations suggest that Lars2 downregulation may contribute to the cognitive deficits observed in our study." (PMID 40806623, 2025). "The coordinated downregulation of mitochondrial genes (Lars2, Vstm2l) alongside KEAP1-NFE2L2 pathway suppression suggests potential molecular pathways whereby IH exposure may affect cellular antioxidant defenses and mitochondrial function, possibly contributing to cognitive impairment." (PMID 40806623, 2025).
type 2 diabetes (3 papers, 2021 to 2023). "Variants in LARS2 have also been found to correlate with the risk of type 2 diabetes." (PMID 36158645, 2022). "Interestingly, single nucleotide mutations in Lars2, perhaps induced by the accumulation of oxidative stress stimulated by episodes of hyperglycemia and hyperinsulinemia, has been implicated as a novel type 2 diabetes susceptibility gene." (PMID 33679877, 2021).
bipolar disorder (2 papers, 2019 to 2023). A disorder of the brain that causes unusual shifts in mood, energy, activity levels and the ability to carry out day-to-day tasks. "Bipolar disorder and schizophrenia may be pathophysiologically attributed to the accumulated 3243A>G mutation of LARS2 in the brain." (PMID 31358688, 2019).
nasopharyngeal carcinoma (2 papers, 2017 to 2025). A carcinoma arising from the nasopharyngeal epithelium. "Recent studies have found a close association between LARS2 and the occurrence of nasopharyngeal carcinoma." (PMID 40230854, 2025).
non-small cell lung carcinoma (2 papers, 2022 to 2025). A group of at least three distinct histological types of lung cancer, including non-small cell squamous cell carcinoma, adenocarcinoma, and large cell carcinoma. "Previous studies have indicated that LARS2 plays a role in various types of cancer, including non-small cell lung cancer, gastric cancer, and acute myelocytic leukemia." (PMID 36158645, 2022).
renal fibrosis (2 papers, 2024 to 2025). A final common manifestation of a wide variety of chronic kidney diseases characterized by glomerulosclerosis and tubulointerstitial fibrosis. "Overexpression of LARS2 can lead to mitochondrial dysfunction and increased levels of reactive oxygen species, causing renal epithelial cells to transition from a functional state to a fibrotic state, thereby promoting renal fibrosis." (PMID 40230854, 2025). "Our findings highlight Rtn3 as a critical regulator of cellular transitions, particularly in renal epithelial and endothelial cells, and identify Lars2 as a key downstream effector driving mitochondrial dysfunction and renal fibrosis." (PMID 38937317, 2024). "Interestingly, Lars2 emerged prominently, being highly expressed in the transitional clusters, especially within PDs, PTs, and DCTs - cell types intricately involved in renal fibrosis." (PMID 38937317, 2024).
cocaine addiction (1 paper, 2020). "Twelve DEGs (Myct1, Gm21860, Ninj2, Fam183b, Lars2, Alkbh1, Fgf5, Frmd7, Tm6sf2, Wnt6, Batf3, and Clca1) were found to be regulated inversely among the overlap genes, which may be possible targets of RPA to disrupt the cocaine addiction process." (PMID 32489401, 2020).
hepatoma (1 paper, 2025). "HCS assays indicated that inhibition of LARS2 and ZNF19 contributed to decreased tumor cell proliferation, suggesting a molecular mechanism behind melittin’s anti-hepatoma activity." (PMID 41157110, 2025).
ovarioleukodystrophy (1 paper, 2021). The "ovarioleukodystrophies" comprise a group of rare leukodystrophies associated with primary or premature ovarian failure. "Mutations in LARS2 cause Perraut syndrome, a rare autosomal recessive disorder causing sensory sensorineural hearing loss in both genders and ovarioleukodystrophy in females." (PMID 34321020, 2021). "It remains to be determined whether Lars2 affects mitochondrial function in a gender dependent manner and whether dysfunction of brain endothelial cells contributes to the ovarioleukodystrophy." (PMID 34321020, 2021).
periodontitis (1 paper, 2024). An acute or chronic inflammatory process that affects the tissues that surround and support the teeth. "Comparing the Average global expression profile of neutrophils from healthy PDL versus neutrophils from PDL with periodontitis revealed increased expression of genes such as Il1b, Il1rn, Cebpb, Colec12, Ptgs2, Zfp36, Egr1, Atf3, Csf1, and Lars2 in periodontitis." (PMID 39588378, 2024).
Stroke (1 paper, 2025). Sudden impairment of blood flow to a part of the brain due to occlusion or rupture of an artery to the brain. "Gene Ontology functional enrichment analysis indicated that stroke-associated genes predominantly regulate mitochondrial maintenance, with leucyl-tRNA synthetase 2 (Lars2) markedly upregulated in post-stroke microglia." (PMID 40681356, 2025). "The lack of compensatory mitochondrial repair in Mc contributes to pro-inflammatory polarization, positioning Lars2 as a mitochondrial checkpoint linking stroke-induced microglial reprogramming to neuroinflammation." (PMID 40681356, 2025).